UCP1 (uncoupling protein 1)
Diseases named in the same sentence as UCP1 in open-access papers (continued):
Sharing a sentence is not in itself a finding about the gene and the disease.
Obesity (continued). "UCP1 expression in BAT is known as a significant component of whole body energy expenditure, at least in small rodents, and its dysfunction contributes to the development of obesity." (PMID 22611357, 2012). "No other significant associations between any SNP and hypertension, hyperlipidemia and diabetes were noted after correction for BMI and no significant synergistic effect between FTO and UCP-1 SNPs with obesity were noted." (PMID 23134754, 2012). "The SNPs rs2270565 and rs12502572 from the UCP-1 were not correlated with obesity and obesity related phenotype." (PMID 23134754, 2012). "The induction of UCP1-expressing beige adipocytes within WAT (browning) and the activation of BAT have gained increasing attention for their ability to improve glucose and lipid profiles and enhance whole-body energy expenditure, thereby contributing to obesity prevention and management." (PMID 41535542, 2026). "Alpha-KG not only increases the expression of thermogenic genes (i.e., Ucp1, Dio2, and Cidea) in the BAT, but also enhances lipolysis in the WATs through OXGR1-dependent adrenal activation, and as a result, administration of exogenous α-KG prevents HFD-induced obesity in mice." (PMID 40959283, 2025). "Strategies targeting brown adipose tissue growth and UCP1 activation, such as pharmacological triggering of β3-adrenergic receptors in adipocytes, offer therapeutic approaches to combat diabetes, obesity, and related diseases, even in the absence of natural stimuli." (PMID 40104293, 2025). "Given the inverse expression pattern of miR-27a/b and Ucp1 observed during high-fat diet (HFD) exposure, we hypothesized that miR-27a/b may contribute to impaired browning capacity of white adipose tissue (WAT) in diet-induced obesity." (PMID 40777263, 2025). "While our findings highlight the anti‐obesity potential of E. conferta extract, further research is needed to clarify its molecular mechanisms, particularly its role in thermogenesis, adipocyte differentiation, and metabolic pathways (e.g., AMPK, PPARγ, and UCP1)." (PMID 40444128, 2025). "However, such repression of UCP1 expression is not typically observed in conditions like obesity and diabetes." (PMID 40149950, 2025). "Similarly, the browning of WAT is known to require the expression of the thermogenic protein UCP1, as these phenotypic changes activate thermogenesis, promoting the browning of WAT, which may be a therapeutic approach to treat obesity." (PMID 40332049, 2025). "The anti-obesity properties of RES may be attributed to its ability to inhibit adipogenesis, increase mitochondrial capacity and stimulate fat oxidation, stimulate WAT browning, upregulate UCP1, and enhance thermogenesis." (PMID 40422907, 2025). "Therefore, the present study will be conducted with the aim of determining the effects of supplementation with N-acetylcysteine on the expression of UCP1, DIO2 DIO3 genes as well as thyroid hormone alpha and beta receptors genes in visceral fat tissue of adults with obesity." (PMID 38702594, 2024). "In contrast, none of the interventions targeting obesity—whether a six-week course of aerobic exercise, cold water exposure, or their combination—resulted in a significant change in UCP1 gene expression." (PMID 40071055, 2024). "This is evidenced by the observation that VDRKO mice are resistant to diet-induced obesity due to increased expression of Ucp1, 2, and 3, as well as stimulated fatty acid oxidation in both WAT and BAT, and overexpression of VDR in adipocytes reduces thermogenesis in WAT and BAT, leading to obesity." (PMID 38928386, 2024). "Interestingly, UCP1KO animals also exhibit protection from diet-induced obesity due to increased shivering to compensate for a lack of UCP1." (PMID 38212382, 2024). "Obesity (P = 0.074), cold water exposure (P = 0.59), aerobic exercise (P = 0.347), and the combined intervention (P = 0.91) did not have any significant impact on UCP1 levels." (PMID 40071055, 2024).
Obesity (continued). "In the present study, SKO-001 administration resulted in reduced adipocyte size, along with increased levels of UCP-1, an important marker of browning, suggesting that SKO-001 may induce adipocyte browning, which may partly contribute to its anti-obesity effects by stimulating energy metabolism." (PMID 36729332, 2023). "The main aim of the present investigation was thus to establish to what extent this very large amount of UCP1 and recruited BAT could counteract the development of obesity that is expected to occur in mice fed a high-fat-diet and housed at a thermoneutral temperature." (PMID 37499977, 2023). "In summary, absence of UCP1 not only hallmarks obesity, but importantly, UCP1 may disappear from the subcutaneous adipose tissue before the onset of overweight." (PMID 38069028, 2023). "In addition to the over-representation of obesity-associated genes in UCP1- samples, our NGS analysis identified a reduced expression of genes associated with obesity protection when UCP1 was absent." (PMID 38069028, 2023). "Consumption of fermented barley may be beneficial in inhibiting diet‐induced obesity, without suppressing energy intake by enhancing the expression of UCP1 level." (PMID 38455221, 2023). "Thus, even excluding those ‘negative’ outcomes that are ‘exceptions’ because the basic criteria of a high-fat diet and thermoneutrality have clearly not been met, not all published studies show an obesity-promoting effect of the absence of UCP1." (PMID 37661736, 2023). "The absence of UCP-1 augmented obesity in high-fat and cafeteria-fed mice." (PMID 36771240, 2023). "Why is there no obesity-promoting effect of UCP1 knockout at normal housing temperatures?" (PMID 37661736, 2023). "UCP1 null mice are resistant to diet-induced obesity regardless of the environmental temperature, suggesting that comparable mechanisms may be operational in the context of diet-induced thermogenesis." (PMID 36088207, 2023). "Moreover, to the best of our knowledge, there are no studies on UCP1 knock-out animals, thus not allowing the confirmation that the promising anti-obesity effects of dietary polyphenols derive exclusively from the modulation of the browning process in vivo." (PMID 37298226, 2023). "Also, specially generated dual UCP1 reporter mice have been used; in these strains no obesity-inducing effect has been reported to have been observed." (PMID 37661736, 2023). "The mice with recruited brown adipose – when transferred to thermoneutrality – could be expected to increase their obesity at a similar rate, were it not for the large amount of UCP1 that they had acquired." (PMID 37499977, 2023). "In addition, TFRC levels in fat are negatively correlated with BMI of human participates and positively correlated with thermogenic marker gene UCP1 levels in human biopsies, suggesting the close correlation of TFRC levels with thermogenic adipocytes and obesity progression in human." (PMID 37646182, 2023). "This makes it plausible that the absence of UCP1 increases the vulnerability to obesity." (PMID 38069028, 2023). "Maintenance of mouse APOA4 levels in the small intestine and plasma elevates UCP1-dependent BAT thermogenesis and energy expenditure and attenuates HFD-induced gains in body weight, fat mass, and plasma lipids, leading to protection against HFD-induced obesity in mice." (PMID 36835642, 2023). "Conversely, the specific deletion of METTL3 in the BAT reduces the expression of Prdm16 and UCP1 transcripts, which impairs BAT maturation, thus resulting in a marked reduction in BAT-mediated adaptive thermogenesis and high-fat diet (HFD)-induced obesity and systemic insulin resistance." (PMID 35982903, 2022). "Mice lacking UCP1 become obese when they are fed in a thermoneutral environment or when they grow old, indicating a crucial role of mitochondrial heat production in energy homeostasis and obesity." (PMID 35043013, 2022).
Obesity (continued). "When DIT occurs, the more UCP‐1 present in BAT may limit obesity development during the HFD exposure, but it will not prevent obesity." (PMID 35510321, 2022). "UCP1 mRNA expression in had significant negative correlations with obesity-related markers." (PMID 36532520, 2022). "Increasing evidence suggests that UCP-1 ablation occurs in the development of obesity under thermoneutral conditions, and the over-expression of UCP-1 resulting in thermogenesis could prevent the development of obesity." (PMID 36145056, 2022). "Thus, the induction of diabetes and obesity by the HFD seems related mainly to UCP1 and UCP2 expression in adipose tissue, but not to the expression of UCP2 and UCP3 in skeletal muscle." (PMID 35323702, 2022). "AMPK has been highlighted as a target for obesity prevention and therapy because of its role in suppressing fatty acid synthesis and inducing β-oxidation by inhibiting ACC and SREBP1, as well as in the development of mitochondrial biogenesis and adipocyte browning by activating UCP1." (PMID 36010531, 2022). "Given that genetic ablation of p38 in adipose tissues facilitated WAT browning upon cold stress and prevented diet-induced obesity and Sal A inhibited p38 MAPK signal pathway in variety of cells, we subsequently analyzed the possibility of p38-mediated UCP-1 induction in Sal A-treated adipocytes." (PMID 34122060, 2021). "Genetic ablation of UCP1 may not influence the IL-25–mediated anti-obesity effect because IL-25 reduced body weight gain and eWAT mass, lowered liver mass in obese UCP1+/+ as effectively as in obese UCP1−/− mice." (PMID 34351905, 2021). "This elevation in basal metabolic rate masks the effects of diet-induced thermogenesis mediated through β-adrenergic driven activation of BAT UCP1 compared to housing mice at thermoneutrality (TN, 29–30 °C) as evidenced by the development of obesity in mice lacking UCP1 at TN but not RT." (PMID 34453052, 2021). "However, given the association between obesity and NAFLD, and lack of data in female mice, we evaluated the influence of EPA supplementation on body weight in the WT and UCP1 KO groups in both male and female mice." (PMID 34829779, 2021). "The UCP1 molecule is strongly expressed in brown adipose tissue (BAT), which promotes whole body energy expenditure, and its protein aberration leads to the development of obesity, although most fat is accumulated in the white adipose tissue (WAT), where UCP1 is absent." (PMID 34069132, 2021). "Other recent work develops the idea that GCs can induce obesity independent of the UCP1." (PMID 34445209, 2021). "However, CME ameliorated HFD increased food intake, body weight gain, hyperglycemia and dyslipidemia through normalization of HFD reduced leptin, adiponectin and UCP1 synthesis and production as well as its antioxidant activity suggesting that CME is a potent anti-obesity agent." (PMID 32197395, 2020). "Moreover, in obesity models (diet-induced-obesity and ob/ob mice), intraperitoneal injection of leptin increases BAT UCP1 mRNA levels and activity without causing significant changes in mice locomotor activity." (PMID 32069871, 2020). "Stimulation of BAT using a β3 adrenoreceptor agonist in obese Sprague–Dawley rats increased resting metabolic rate (by 40%–45%), increased UCP1 content in BAT, reduced abdominal white adipose tissue (WAT), reversed diet-induced obesity and caused browning of WAT despite no change in food intake." (PMID 31220223, 2020). "Importantly, protection against diet-induced obesity was maintained when the mice were housed under thermoneutral conditions (for mice this is ∼30°C), implying that the effect was not reliant on UCP1-dependent thermogenesis." (PMID 32539124, 2020). "Together, EPA and DHA supplementation can compromise energy expenditure and dissipation in brown adipocyte independent of UCP1, which may be positively correlated with intramuscular lipid accumulation and obesity." (PMID 32595696, 2020).
Obesity (continued). "These AKG‐induced anti‐obesity effects include decreases in body weight gain, fat mass, gWAT and iWAT weight, adipocyte size of gWAT and iWAT, and RER, as well as increases in lean mass, oxygen consumption, ATGL protein in gWAT, phosphorylation of HSL in both iWAT and gWAT, and UCP1 protein in BAT." (PMID 32104923, 2020). "UCP1, PPARG coactivator 1 alpha (PPARGC1A), transcription factor A, mitochondrial (TFAM), T-box transcription factor 1 (TBX1), and solute carrier family 27 member 1 (SLC27A1) expression was assayed in SAT and VAT samples, obtained during sleeve gastrectomy from 62 patients with obesity." (PMID 31440209, 2019). "Thus, even in an obesity-resistant mouse strain, obesity is induced and amplified in the absence of UCP1." (PMID 30807213, 2019). "Furthermore, recent studies have confirmed an anti-obesity effect for tranylcypromine even in mice invalidated for the uncoupling protein-1 (UCP1) involved in non-shivering thermogenesis and in beiging of WAT." (PMID 30650583, 2019). "Thus, the obesity-reducing effect of UCP1 is not restricted to a particular, and perhaps not representative, mouse strain." (PMID 30807213, 2019). "However, one study in rodents indicates that mast cells have several negative effects in the context of obesity, including the suppression of UCP1 in BAT33." (PMID 31209239, 2019). "This resistance to obesity occurs during cold stress (4~20°C), but is absent at thermoneutrality (27°C), suggesting the presence of alternative UCP1-independent non-shivering thermogenesis that is less efficient than UCP1-dependent thermogenesis." (PMID 31730675, 2019). "It upregulates uncoupling protein-1 (UCP-1) expression, which indicates the conversion of white adipocyte into thermogenic beige adipocytes and increases in energy expenditure, unraveling the potentials of SERM in the management of obesity by upregulation of energy expenditure." (PMID 31470850, 2019). "The absence of UCP1 augmented obesity (weight gain, body fat mass, %body fat, fat depot size) in high-fat diet- and cafeteria-fed mice, with a similar or lower food intake, indicating that, when present, UCP1 indeed decreases metabolic efficiency." (PMID 30807213, 2019). "As UCP1, a key regulator of thermogenesis, is mainly expressed in BAT and brite/beige adipocytes, its increased expression in WAT could be considered as an adequate target for the prevention and treatment of obesity." (PMID 30200432, 2018). "In an obesity and hyperglycemia animal model, thiazolidinedione derived partial PPARγ agonist GQ-16 increased UCP-1 protein expression in interscapular brown adipose tissue (BAT) and in epididymal and inguinal white adipose tissue (WAT) to induce WAT browning and treat obesity." (PMID 29849705, 2018). "Importantly, Tfe3 KO mice showed down‐regulation of genes involved in thermogenesis, including Ucp1 and Ucp3, and oxidative genes such as Pparα in the BAT, which account, at least partially, for their reduced energy expenditure and diet‐induced obesity." (PMID 28283651, 2017). "In addition, it has been reported that remarkable UCP1 expression in WAT may result in increased fatty acid oxidation in adipocytes and lead to resistance to diet‐induced obesity." (PMID 27357657, 2016). "Thus, fish oil intake can induce UCP1 expression in classical brown and beige adipocytes via the SNS and TRPV1, and may contribute to an effective treatment for obesity." (PMID 26673120, 2015). "Moreover, core body temperature and energy expenditure of WT mice increased during the light cycle, and obesity and core body temperature alterations were independent of changes in UCP1 and occurred in UCP1 knockout mice." (PMID 24586592, 2014). "The season-specific effects of UCP1 on VFA were consistent with a previous finding that active BAT was more frequently found in winter than in summer, and supported the importance of cold stress in BAT activation and the significance of BAT in the development of obesity in adult humans." (PMID 24086366, 2013).
Obesity (continued). "For example, mice with a targeted ablation of BAT due to a tissue-specific transgenic expression of diphtheria toxin from the uncoupling protein 1 (UCP1) gene promoter are obese, although it is possible that the obesity of this mouse model is caused by hyperphagia rather than reduced thermogenesis." (PMID 21698184, 2011). "Our results indicate that cyclooxygenase-dependent induction of UCP1 expression in white adipose tissues is important for diet-induced thermogenesis providing support for a surprising role of COX activity in the control of energy balance and obesity development." (PMID 20613988, 2010). "The anti-obesity role of UCP1 was challenged by the finding that UCP1 KO mice were not obese." (PMID 20613988, 2010). "Thus, it is surprising that inactivation of UCP1 did not potentiate diet‐induced obesity." (PMID 39569747, 2025). "We aim to address the feasibility of utilizing BAT modulators for weight reduction in obese individuals, as recent studies suggest that BAT’s contributions to energy expenditure along with Ucp1-dependent and -independent pathways may or may not rectify energy imbalance characteristic of obesity." (PMID 39087083, 2024). "However, UCP1 KO mice did not respond to the anti-obesity benefits of CQA administration." (PMID 36517893, 2022). "Significant decrements in the expression of Ucp1 and Pgc1a mRNA as well as UCP1 protein levels induced by prolactin but not by HFD, indicate that prolactin, independently of the diet or obesity, may predispose to the development of an obese phenotype by lowering the thermogenic capacity of BAT." (PMID 35757410, 2022). "Therefore, UCP1 fails to protect against diet-induced obesity due to insufficient activation." (PMID 35269549, 2022). "As stimulation of TrkC by NT3 mimics the effects of β-adrenoceptors on UCP1 expression and adipocyte size in human and rodents, a drug selectively acting on TrkC, abundantly expressed in WAT and BAT, could be a promising pharmacological target in the management of obesity." (PMID 33815288, 2021). "Similarly, CRISPR/CAS9-mediated reconstitution of UCP1 in WAT of pigs led to significantly decreased fat mass and improved energy expenditure, suggesting the therapeutic potential of modulating WAT phenotype by activation of key thermogenic genes for fighting obesity and metabolic syndrome." (PMID 33897620, 2021). "Brown adipose tissue (BAT), the primary source of thermogenesis in infants and small mammals may represent a promising therapeutic target to treat obesity by promoting energy expenditure through non-shivering thermogenesis mediated by mitochondrial uncoupling protein 1 (UCP1)." (PMID 34831253, 2021). "The initial increase in Ucp1 transcripts in response to HFD feeding in brown fat in rodents is followed by a decline at longer time points, thus raising a tempting speculation that the downregulation of Clstn3β in BAT of HFD-fed animals occurs prior to obesity-induced decline in Ucp1 transcripts." (PMID 33101212, 2020). "Additionally, we include a summary of other newly discovered pathways, including non-AR signaling- and non-UCP1-dependent mechanisms, which could be potential targets for the treatment of obesity and its related metabolic diseases." (PMID 32351446, 2020). "Correspondly, a pharmacological approach to increase UCP1 expression and activates of BAT thermogenesis and (or) recruits brown-like brite/beige cells in WAT may be a safer avenue to enhance whole-body energy expenditure, one complementary and alternative medicine for anti-obesity therapy." (PMID 32190098, 2020). "Thus, it was thought that the taurine-mediated decreased expression of PGC-1α and UCP-1 in iWAT is not an artefact but could be induced in obesity-resistant ICR mice." (PMID 32466447, 2020). "Thus, even in the obesity-resistant 129S2/sv mice, the absence of UCP1 promoted additional obesity." (PMID 30807213, 2019).